CELF5 (CUGBP Elav-like family member 5)
Description:
RNA-binding protein implicated in the regulation of pre-mRNA alternative splicing. Mediates exon inclusion and/or exclusion in pre-mRNA that are subject to tissue-specific and developmentally regulated alternative splicing. Specifically activates exon 5 inclusion of cardiac isoforms of TNNT2 during heart remodeling at the juvenile to adult transition. Binds to muscle-specific splicing enhancer (MSE) intronic sites flanking the alternative exon 5 of TNNT2 pre-mRNA.
Synonyms: CELF-5; BRUNOL5; BRUNOL-5
Tractability: PROTAC: ubiquitination databases record sites on it; its protein half-life has been measured.
Gene: Protein-coding gene on chromosome 19 (3,224,650 to 3,297,076, forward strand). Ensembl gene ENSG00000161082.
Subcellular location: Nucleus; Cytoplasm
Gene Ontology:
Molecular function: protein binding; pre-mRNA binding; nucleic acid binding; RNA binding
Biological process: regulation of alternative mRNA splicing, via spliceosome; mRNA splice site recognition
Cellular component: nucleus; ribonucleoprotein complex; cytoplasm
Genetic constraint (gnomAD): Loss-of-function variants: 6 observed, 47.69 expected, observed/expected ratio (o/e) 0.13, 90% interval 0.068 to 0.25. The upper end of that interval is the gene's LOEUF score, 0.25, which puts it in group 1 of 6, group 1 being the genes least tolerant of losing a copy. Missense variants: 401 observed, 648.4 expected, observed/expected ratio (o/e) 0.62, 90% interval 0.57 to 0.67. Synonymous variants: 271 observed, 275.51 expected, observed/expected ratio (o/e) 0.98, 90% interval 0.89 to 1.09.
Homologues: Orthologues: chimpanzee CELF5 (100% identical), dog CELF5 (99% identical), pig CELF5 (99% identical), mouse Celf5 (89% identical), rat Celf5 (88% identical), tropical clawed frog celf5 (85% identical), zebrafish celf5a (74% identical), zebrafish celf5b (56% identical), Caenorhabditis elegans unc-75 (52% identical), Drosophila melanogaster bru3 (47% identical). Paralogues in human: CELF4 (66% identical), CELF6 (65% identical), CELF3 (63% identical), CELF1 (47% identical), CELF2 (47% identical), RBM28 (23% identical).
Diseases named in the same sentence as CELF5 in open-access papers:
CELF5 is named in the same sentence as 5 diseases in open-access papers, as found by Europe PMC text mining. Sharing a sentence is not in itself a finding about the gene and the disease. The quoted sentences say what the papers report.
cardiomyopathies (1 paper, 2015). "Consequently, other RNA-binding proteins such as CELF-3, CELF-5, RBM24, RBM25 and LUC7L3 have been linked to the development of cardiomyopathies." (PMID 26116573, 2015).
glioma (1 paper, 2019). A benign or malignant brain and spinal cord tumor that arises from glial cells (astrocytes, oligodendrocytes, ependymal cells). "Additionally, analysis based on 1,018 Chinese glioma patients suggested that CELF5 (P < 0.001), GSG1L (P = 0.002), AMACR (P < 0.001), CYP27A1 (P < 0.001), CYP46A1 (P < 0.001), and CH25H (P = 0.046) were all prognostic indicators in Kaplan-Meier survival analysis." (PMID 32117422, 2019).
cancer (1 paper, 2019). A tumor composed of atypical neoplastic, often pleomorphic cells that invade other tissues. "While RBFOX3, RBM11 (RNA binding motif protein 11) and DDX25 (DEAD-box helicase 25) are generally downregulated in cancers compared to normal cells, the dysregulation of CELF5, ELAVL2 and ESRP1 is dependant on the type of cancer." (PMID 30704403, 2019).
neurological disorders (1 paper, 2022). "Like the previous comparison, several of these transcripts, such as CELF5, DEPTOR, DLG2, OPTN and STX3, have been linked to brain functions and neurological disorders, supporting the fact that these hnRNP proteins can work in a network to regulate at least specific sets of targets." (PMID 36267332, 2022).
tumor (1 paper, 2019). "CELF5 was low-expressed in tumor cell line; AMACR, CYP27A1, CYP46A1, and CH25H were high-expressed in tumor cell line in CCLE." (PMID 32117422, 2019).